PAK4 (p21 (RAC1) activated kinase 4)
Diseases named in the same sentence as PAK4 in open-access papers (continued):
Sharing a sentence is not in itself a finding about the gene and the disease.
non-small cell lung carcinoma (8 papers, 2015 to 2024). A group of at least three distinct histological types of lung cancer, including non-small cell squamous cell carcinoma, adenocarcinoma, and large cell carcinoma. "PAK4 knockdown in non-small cell lung cancer cells reduced LIMK1 phosphorylation, decreasing cell migration and invasion." (PMID 39337621, 2024). "However, little is known about the expression and biological function of PAK4 in human non-small cell lung cancer (NSCLC)." (PMID 25975262, 2015). "In addition, in non-small cell lung cancer (NSCLC), a respiratory tumor, PAK4 is considered to be an independent predictor of poor survival." (PMID 35800076, 2022).
oral squamous cell carcinoma (8 papers, 2015 to 2025). "Fisetin acts on oral squamous cell carcinoma by targeting PAK4 (p21-activated kinase 4)." (PMID 33953688, 2021). "In oral squamous cell carcinoma (OSCC), LINC01296, the ceRNA of miR-485-5p, regulates the expression of p21-activating kinase 4 (PAK4); promotes OSCC cell cycle, proliferation, migration, and invasion, and inhibits apoptosis." (PMID 39901673, 2025).
endometrial cancer (7 papers, 2014 to 2024). Primary or metastatic malignant neoplasm involving the endometrium (mucous membrane that lines the endometrial cavity). "We found lower expression of cytoplasmic Pak4 was associated with poorer prognosis in endometrial cancers." (PMID 26218748, 2015). "The correlation between Pak4 and ERα signaling not only reveals an underlying mechanism of estrogen-related tumor progression, but also provides a rationale for multi-targeted therapies against endometrial cancer." (PMID 28978098, 2017). "To explore this possibility, we have investigated the relationship between Pak4 and estrogen signaling in endometrial cancer." (PMID 28978098, 2017). "In summary, our results demonstrate the presence of a positive feedback loop between Pak4 and ERα signaling in endometrial cancer." (PMID 28978098, 2017). "Pak1, cytoplasmic and nuclear Pak4 and nuclear p-Pak4 are involved in the pathogenesis of endometrial cancer especially in postmenopausal women." (PMID 26218748, 2015). "Significantly higher cytoplasmic Pak4 expression was also found in secretory endometrium than complex hyperplasia (P = 0.047) and endometrial cancers (P = 0.036)." (PMID 26218748, 2015). "Cytoplasmic and nuclear Pak4 showed weak expression in atrophic endometrium and moderate to strong expression in secretory, proliferative, hyperplastic endometrium and endometrial cancers." (PMID 26218748, 2015). "We found significantly higher Pak1, cytoplasmic and nuclear Pak4 and nuclear p-Pak4 expression in endometrial cancers than atrophic endometrium." (PMID 26218748, 2015). "Pak1, cytoplasmic and nuclear Pak4 and nuclear p-Pak4 are involved in the pathogenesis of endometrial cancer and can be potential therapeutic targets especially in postmenopausal women." (PMID 26218748, 2015). "Pak1, cytoplasmic and nuclear Pak4 and nuclear p-Pak4 was significantly overexpressed in endometrial cancer when compared to atrophic endometrium (all P<0.05)." (PMID 26218748, 2015). "We tested the hypothesis that a positive feedback loop exists in which estrogen stimulates Pak4 expression and activation, which in turn promotes ERα trans-activation, and endometrial cancer cell proliferation." (PMID 28978098, 2017). "Furthermore, patients with endometrial cancers with lower cytoplasmic Pak4 expression showed poorer survival (P = 0.026)." (PMID 26218748, 2015). "However, significant difference of nuclear Pak4 expression only observed between endometrial cancers and atrophic endometrium (P = 0.026)." (PMID 26218748, 2015). "Cytoplasmic Pak4 can be potential prognostic marker in endometrial cancer." (PMID 26218748, 2015). "The roles of Pak4 in endometrial cancer need to be further elucidated." (PMID 26218748, 2015). "Increased expression of Pak1 and Pak4 was also detected in endometrial cancer cell lines." (PMID 26218748, 2015). "Furthermore, we have observed a nuclear localization of Pak4, especially the activated, phosphorylated Pak4 form (p-Pak4ser474) in endometrial cancer tissues, suggesting that Pak4 might activate ERα and contribute to estrogen-induced EC pathogenesis." (PMID 28978098, 2017). "Thus inhibition of Pak4-ERα signaling may represent a novel therapeutic strategy against endometrial carcinoma." (PMID 28978098, 2017). "Similarly, PAK4 promotes the cell invasion of choriocarcinoma and endometrial cancer." (PMID 27765920, 2016). "Therefore, the emergence of Pak4 inhibitors suggests that targeting Pak4 expression or activity may represent a novel strategy to increase the response to hormonal treatment in endometrial cancer." (PMID 28978098, 2017). "Pak4 was found in the cytoplasm and in the nucleus, whereas mild cytoplasmic and strong nuclear p-Pak4 immunostaining was observed in human RL95-2 endometrial cancer cells." (PMID 28978098, 2017). "High PAK4 expression lacked significant negative prognosis in these cancers, although a trend towards worse outcomes existed in endometrial cancer." (PMID 38424218, 2024).
endometrial cancer (continued). "Functionally, knockdown of Pak1, but not Pak4, in endometrial cancer cell line led to reduced cell proliferation along with reduced cyclin D1, estrogen receptor (ERα) and progestogen receptor (PR) expression." (PMID 26218748, 2015). "Kaplan-Meier-survival analyses revealed that lower expression of cytoplasmic Pak4 (P = 0.026), but not Pak1, nuclear and cytoplasmic p-Pak2, nuclear Pak4, nuclear and cytoplasmic p-Pak4, resulted in a poorer survival in endometrial cancer patients." (PMID 26218748, 2015). "In this study, expression of Pak1, p-Pak2 Ser20, Pak4, pPak4 Ser474 in 21 normal endometrium, 16 hyperplastic endometrium without atypia, 17 atypical complex hyperplasia and 67 endometrial cancers was assessed by immunohistochemistry and correlated with clinicopathological parameters." (PMID 26218748, 2015).
Parkinson disease (7 papers, 2019 to 2025). A progressive degenerative disorder of the central nervous system characterized by loss of dopamine producing neurons in the substantia nigra and the presence of Lewy bodies in the substantia nigra and locus coeruleus. "In fact, PAK4 has been associated with Parkinson’s disease (PD): patient substantia nigra exhibited reduced PAK4 expression, in vivo neuronal ablation of PAK4 increased aSYN aggregation and PAK4 gain-of-function reduced aggregation, although this impact was suggested to be indirect." (PMID 41282267, 2025). "Among group II PAKs, PAK4 activity was significantly reduced in the substantia nigra of patients with and rodent models of Parkinson’s disease." (PMID 33306168, 2022). "Disruptions in PAK4-mediated regulation of CREB activity have also been observed in neurons affected by Parkinson’s disease." (PMID 30755582, 2019).
cervical cancer (6 papers, 2015 to 2025). A primary or metastatic malignant neoplasm involving the cervix. "It was demonstrated that PAK4 was upregulated in cervical cancer tissues, in an association with the cancer’s malignance variables such as FIGO stage, lymph node or distant metastasis and the poor histological grade." (PMID 26411419, 2015). "To explore the mechanism underlying PAK4-induced cisplatin resistance in cervical cancer cells, we examined the activation of PI3K/Akt pathway in the cisplatin-treated Hela and Caski cells, with or without the transfection with siRNA-PAK4 or siRNA-Con." (PMID 26411419, 2015). "The high PAK4 expression was also independently associated with poor prognosis to cervical cancer patients." (PMID 26411419, 2015). "To recognize the prognostic value of PAK4 expression in patients with cervical cancer, we then investigated the association between PAK4 expression and overall survival of cervical cancer patients by Kaplan-Meier analysis and log-rank test." (PMID 26411419, 2015). "To further investigate the association of PAK4 with the poor prognosis of cervical cancer patients, we examined the influence of PAK4 overexpression on the sensitivity of Hela and Caski cells to cisplatin." (PMID 26411419, 2015). "Our results demonstrate that PAK4 is closely associated with the development and progression of cervical cancer and confers cisplatin resistance in cervical cancer cells." (PMID 26411419, 2015). "And the univariate analysis demonstrated that the FIGO stage (P = 0.0026), the lymph node metastasis (P = 0.0048) and the histological grade (P = 0.0375), and PAK4 expression (P = 0.0014) were significantly associated with overall survival of cervical cancer patients." (PMID 26411419, 2015). "The PI3K/AKT pathway is activated by PAK4 and facilitates cisplatin resistance in cells of cervical cancer." (PMID 38238316, 2024). "It was reported in 2017 that although PAK1 and PAK4 are highly expressed in HeLa cervical cancer cells, only PAK4 knockdown attenuates expression of HIF-1α in hypoxia." (PMID 29443911, 2018). "Those patients with higher FIGO stage (p = 0.00822), with lymph node (p = 0.00525) or distant (p = 0.02105) metastasis, or with poor histological grade (p = 0.03464) presented significantly higher level of PAK4 mRNA in their cervical cancer specimens." (PMID 26411419, 2015). "In summary, this study has confirmed the significant prognostic role of PAK4 level in cervical cancer patients and has recognized the regulatory role in cervical cancer progression." (PMID 26411419, 2015). "This study has confirmed the significant prognostic role of PAK4 level in cervical cancer patients and has recognized the regulatory role in cervical cancer progression." (PMID 26411419, 2015). "This study was designed to explore the potential prognosis value of PAK4 in cervical cancer, and then to investigate the regulatory role of PAK4 in the cisplatin resistance in cervical cancer cells." (PMID 26411419, 2015). "High PAK4 level is correlated with the advanced stage cervical cancer, and is an independent factor for predicting the clinical prognosis of patients with cervical cancer." (PMID 26411419, 2015). "Moreover, our study has indicated that PAK4 also confers the chemoresistance of cervical cancer cells in a PI3K/Akt-dependent way." (PMID 26411419, 2015). "However, the high PAK4 expression was markedly associated with the FIGO stage, lymph node metastasis, distant metastasis and histological grade of these cervical cancer patients." (PMID 26411419, 2015). "Thus, our study indicates PAK4 as a promising marker for cervical cancer treatment." (PMID 26411419, 2015). "Moreover, PAK4 confers cisplatin resistance in cervical cancer Hela or Caski cells." (PMID 26411419, 2015). "In contrast to the role of PAK4 as an effector of PI3K, PAK4 may act upstream of PI3K in promoting cisplatin resistance in gastric and cervical cancer cells." (PMID 30755582, 2019).
cervical cancer (continued). "However, the oncogenic role of PAK4 in cervical cancer has not been reported." (PMID 26411419, 2015).
lymph node metastasis (6 papers, 2015 to 2024). "In GC, high PAK4 expression is not only associated with deeper invasion depth but also with more severe lymph node metastasis, distant metastasis, advanced tumor stage, and recurrence." (PMID 35800076, 2022). "Immunohistochemical study revealed that high PAK4 expression is associated with larger tumor size, lymph node metastasis, and advanced stage cancer in 93 invasive breast carcinoma patients." (PMID 28407679, 2017). "High level PAK4 expression was associated with more lymph node metastasis (p = 0.027), larger tumor size (p = 0.007), and advanced AJCC stages (p = 0.012)." (PMID 28407679, 2017). "In the present study, increased PAK4 expression was associated with differentiation, lymph node metastasis, distant metastasis, clinical stage, and an unfavorable prognosis in patients with NSCLC." (PMID 25975262, 2015). "NSCLC patients with upregulated PAK4 tend to have a shorter OS period, and high PAK4 expression is closely related to lymph node metastasis, distant metastasis, and advanced tumor stage." (PMID 35800076, 2022). "Similarly, in CC, high expression of PAK4 is also related to poor OS, lymph node metastasis, distant metastasis, advanced FIGO stage, and poor histological grade." (PMID 35800076, 2022). "Moreover, higher PAK4 staining scores were positively correlated with differentiation, lymph node metastasis, distant metastasis, and clinical stage." (PMID 25975262, 2015). "Another study showed that high expression of PAK4 in COAD is associated with advanced tumor stage and histological grade, but not with the depth of invasion, lymph node metastasis, or distant metastasis." (PMID 35800076, 2022).
acute myeloid leukemia (5 papers, 2021 to 2025). Acute myeloid leukemia (AML) is a group of neoplasms arising from precursor cells committed to the myeloid cell-line differentiation. "Currently there is one active Phase I trial of the dual PAK4/NAMPT inhibitor KPT-9274, in patients with relapsed and refractory acute myeloid leukemia (NCT04914845)." (PMID 40526635, 2025). "Two ongoing, multicenter, promising trials of PAK4 inhibitors are testing the safety of the orally bioavailable dual inhibitors ATG-019 and KPT-9274, targeting the PAK4 and PAK4 and NAMPT in advanced solid tumors, in non-Hodgkin’s lymphoma, and in relapsed acute myeloid leukemia." (PMID 36830998, 2023). "In addition, we found that the expression of PAKs in most tumors was distinctly higher than that in the corresponding normal tissues, while PAK1, PAK2 and PAK4 showed the most significant differences but only in Cholangiocarcinoma (CHOL) and Acute Myeloid Leukemia (LAML)." (PMID 36064705, 2022).
multiple myeloma (5 papers, 2021 to 2024). "High expression of PAK4 promotes myeloma cell proliferation through activation of multiple myeloma anti-apoptotic and survival pathways." (PMID 34307365, 2021). "In multiple myeloma cells, blocking Pak4 resulted into inhibited myeloma cell growth and survival." (PMID 38807162, 2024).
non-Hodgkin lymphoma (5 papers, 2020 to 2025). Distinct from Hodgkin lymphoma both morphologically and biologically, non-Hodgkin lymphoma (NHL) is characterized by the absence of Reed-Sternberg cells, can occur at any age, and usually presents as a localized or generalized lymphadenopathy associated with fever and weight loss. "Additionally, a phase I trial targeting PAK4 in advanced solid tumours and non-Hodgkin lymphoma is currently ongoing (NCT02702492)." (PMID 32915198, 2020). "A first-in-human phase 1 study of KPT-9274, a first-in-class dual inhibitor of PAK4 and NAMPT, in patients with advanced solid malignancies or non-Hodgkin’s lymphoma is ongoing." (PMID 41036084, 2025). "Another clinical trial of an oral dual inhibitor of PAK4 and NAMPT in advanced solid tumors or non-Hodgkin’s lymphoma was terminated due to undisclosed reasons." (PMID 36830998, 2023). "KPT-9274 is a phase 1 first-in-class dual PAK4/NAMPT inhibitor for solid tumor and non-Hodgkin's lymphoma." (PMID 34187548, 2021).
breast tumors (4 papers, 2012 to 2025). "The Pak4 expression pattern—high in breast tumors but low in normal breast tissue—could make Pak4 a promising diagnostic tool for the disease." (PMID 23326684, 2012). "To this end, we analyzed the METABRIC14 dataset and found that PAK4 transcript expression was approximately twofold higher in breast tumors compared with their normal counterparts." (PMID 31399573, 2019). "The Pak4 protein kinase is often overexpressed in breast tumors, but is poorly expressed in normal breast tissue." (PMID 23326684, 2012).
clear cell renal cell carcinoma (4 papers, 2023 to 2024). "This study explored the protein expression levels of UCHL1, SNRNP200, and PAK4 in clear cell renal cell carcinoma (CCRCC) using advanced proteomic techniques." (PMID 39199615, 2024). "PAK4, PAK5, and PAK6 are homologs of CLA4, and PAK6 has also been implicated in clear cell renal cell carcinoma." (PMID 36598488, 2023).
esophageal cancer (4 papers, 2018 to 2024). A primary or metastatic malignant neoplasm involving the esophagus. "Herein, we demonstrate reduced expression of miR-199a-3p in human esophageal cancer specimens and cell lines compared to esophageal epithelial cells, with associated increased expression of PAK4." (PMID 29983868, 2018). "This study was designed to determine the expression levels of miR-199a-3p and PAK4 in esophageal cancer cells, in both human specimens and a panel of cell lines." (PMID 29983868, 2018). "Based on these results, we chose to further evaluate the relationship between miR-199a-3p and PAK4 in esophageal cancer cells." (PMID 29983868, 2018). "Because basal levels of miR-199a-3p are low in all three esophageal cancer cell lines, transfection of pre-miR-199a-3p into these cells was performed in order to assess the effects on PAK4 expression." (PMID 29983868, 2018). "Our results show that miR-199a-3p functions as a tumor suppressor in esophageal cancer cells through repression of PAK4." (PMID 29983868, 2018). "We demonstrate that miR-199a-3p functions as a tumor suppressor in esophageal cancer cells by regulating PAK4 expression through a direct interaction with its mRNA." (PMID 29983868, 2018). "Forced expression of miR-199a-3p decreases expression of PAK4 in esophageal cancer cell lines." (PMID 29983868, 2018). "In addition to providing an initial description of the role of miR-199a-3p in esophageal cancer cells, these data also describe an important role for PAK4 in esophageal cancer." (PMID 29983868, 2018). "In addition, we characterized the interaction between miR-199a-3p and PAK4 mRNA in esophageal cancer cells and elucidated the phenotypic effects of modulating expression of miR-199a-3p in these cells." (PMID 29983868, 2018). "We hypothesized that reduced expression of miR-199a-3p in esophageal cancer cells may lead to increased expression of PAK4." (PMID 29983868, 2018). "The current study is designed to determine whether miR-199a-3p regulates the expression of PAK4 in esophageal cancer cells and to understand the functional consequences of this interaction." (PMID 29983868, 2018). "Pak4 was highly expressed in various tumors, including bladder urothelial carcinoma (BLCA), breast invasive carcinoma (BRCA), cholangiocarcinoma (CHOL), Esophageal carcinoma (ESCA), head and neck cancer (HNSC) and so on." (PMID 38807162, 2024). "Overexpression of PAK4 has been demonstrated in multiple malignancies including breast, prostate, and pancreas, although its role in esophageal cancer has not been well studied." (PMID 29983868, 2018).
liver cancer (4 papers, 2022 to 2023). An epithelial or non-epithelial malignant neoplasm that arises from the liver. "To identify pharmacological means to alter 2D cell migration in liver cancer, we targeted key regulators of the Rho GTPases, including calcium signaling, Rac1, PAK4, LIMK1, MLCK, and actomyosin contractility." (PMID 35241781, 2022). "Future studies targeting these pathways will further delineate the role of PAK4 in liver cancer cell invasiveness." (PMID 35241781, 2022). "Comparing normal liver tissue samples (225 patients) and liver hepatocellular carcinoma (LIHC) samples (371 patients), the expression of the genes: RhoA, Rac1, LIMK1, LIMK2, ROCK1, ROCK2, MLCK2, and PAK4 is upregulated in liver cancer." (PMID 35241781, 2022). "Moreover, ZIC2 regulates the expression of PAK4 by binding to the promoter of PAK4 to promote liver cancer progression." (PMID 37479694, 2023). "Another possibility is that PAK4 may mediate cell migration in liver cancer through other forms of regulation." (PMID 35241781, 2022).